XXYLT1 (xyloside xylosyltransferase 1)
Description:
Alpha-1,3-xylosyltransferase, which elongates the O-linked xylose-glucose disaccharide attached to EGF-like repeats in the extracellular domain of target proteins by catalyzing the addition of the second xylose. Known targets include Notch proteins and coagulation factors, such as F9.
Synonyms: C3orf21; FLJ35155
Tractability: Antibody: UniProt predicts a signal peptide or a membrane-spanning region. PROTAC: ubiquitination databases record sites on it; its protein half-life has been measured.
Gene: Protein-coding gene on chromosome 3 (195,068,284 to 195,271,159, reverse strand). Ensembl gene ENSG00000173950.
Subcellular location: Endoplasmic reticulum membrane
Gene Ontology:
Molecular function: magnesium ion binding; manganese ion binding; UDP-xylosyltransferase activity; xylosyl alpha-1,3-xylosyltransferase activity; glycosyltransferase activity
Biological process: protein O-linked glycosylation via glucose; protein O-linked glycosylation via N-acetyl-galactosamine; protein O-linked glycosylation
Cellular component: endoplasmic reticulum membrane
Genetic constraint (gnomAD): Loss-of-function variants: 20 observed, 25.67 expected, observed/expected ratio (o/e) 0.78, 90% interval 0.55 to 1.13. The synonymous counts are far from expectation, so gnomAD's model fits this gene poorly and the ratio says little. Missense variants: 542 observed, 471.19 expected, observed/expected ratio (o/e) 1.15, 90% interval 1.07 to 1.24. Synonymous variants: 257 observed, 206.04 expected, observed/expected ratio (o/e) 1.25, 90% interval 1.13 to 1.38.
Homologues: Orthologues: chimpanzee XXYLT1 (99% identical), macaque XXYLT1 (98% identical), rabbit XXYLT1 (95% identical), pig XXYLT1 (94% identical), guinea pig XXYLT1 (93% identical), mouse Xxylt1 (93% identical), rat Xxylt1 (93% identical), dog XXYLT1 (92% identical), tropical clawed frog xxylt1 (67% identical), zebrafish xxylt1 (59% identical), Drosophila melanogaster Xxylt (36% identical), Caenorhabditis elegans bgnt-1.4 (6% identical), and 6 more. Paralogues in human: GXYLT2 (20% identical), LARGE2 (20% identical), LARGE1 (19% identical), GXYLT1 (18% identical), B4GAT1 (6% identical).
Diseases named in the same sentence as XXYLT1 in open-access papers:
XXYLT1 is named in the same sentence as 5 diseases in open-access papers, as found by Europe PMC text mining. Sharing a sentence is not in itself a finding about the gene and the disease. The quoted sentences say what the papers report.
lung carcinoma (2 papers, 2017 to 2021). "Our study revealed that the ablation of the C3orf21 gene (XXYLT1) promoted lung cancer MSTO-211H cell proliferation, inhibited apoptosis and accelerated cell migration." (PMID 28422717, 2017).
cancer (4 papers, 2016 to 2022). A tumor composed of atypical neoplastic, often pleomorphic cells that invade other tissues. "Furthermore, the amplification of XXYLT1 has been discovered in various cancer types in which Notch signaling activity is inhibited." (PMID 35335147, 2022). "The amplification of XXYLT1 has been detected in many types of cancers, such as lung, esophagus, and head-and-neck-derived SCC, in which Notch signaling may have a tumor-suppressive role." (PMID 35335147, 2022). "We have recently characterized a Notch‐modifying enzyme Xxylt1 101 that is frequently amplified in specific cancer types lacking loss‐of‐function XXYLT1 mutations." (PMID 27228302, 2016). "Considering that Xxylt1 can negatively regulate Notch activation 102, this may suggest a novel pathway changes to comprise Notch activation in the tumorigenesis of these cancer types." (PMID 27228302, 2016). "Five—Using STRING database, we found that it had interactions with several proteins involved in different cancers such as TXNDC9, GXYLT2, POFUT1, XXYLT1, FLNA, and ZC3H12C." (PMID 35140741, 2021).
XXYLT1 also shares sentences with these, for which no sentence is quoted: tumor (2 papers); lung adenocarcinoma (1); non-small cell lung carcinoma (1).